ADCY10P1 (ADCY10 pseudogene 1)
Gene: Transcribed unprocessed pseudogene on chromosome 6 (41,101,022 to 41,138,727, forward strand). Ensembl gene ENSG00000161912.
Diseases named in the same sentence as ADCY10P1 in open-access papers:
ADCY10P1 is named in the same sentence as 2 diseases in open-access papers, as found by Europe PMC text mining. Sharing a sentence is not in itself a finding about the gene and the disease. The quoted sentences say what the papers report.
cancer (1 paper, 2022). A tumor composed of atypical neoplastic, often pleomorphic cells that invade other tissues. "Furthermore, when expressed at a high level, ADCY10P1 was found to act as a protective lncRNA that can inhibit glycolysis and fatty acid metabolism, crucial for the aggressive proliferation of cancer cells." (PMID 35568893, 2022). "Moreover, we investigated the role of ADCY10P1 in different cancers." (PMID 35568893, 2022).
tumour (1 paper, 2022). "The results revealed that ADCY10P1 plays a role as tumour suppressor in OC." (PMID 35568893, 2022). "In addition, ADCY10P1 acts as a tumour suppressor and inhibits the proliferation, migration, invasion, EMT, glycolysis and fatty acid metabolism of OC cells." (PMID 35568893, 2022).